TNF (tumor necrosis factor)
Diseases named in the same sentence as TNF in open-access papers (continued):
Sharing a sentence is not in itself a finding about the gene and the disease.
tumor (continued). "In general, M1-TAMs exert cytotoxic effects on tumor cells by secreting nitric oxide or producing TNF-α, IFN-γ, or IL-12, and also triggers the activity of NK cells and prime cytotoxic T cells." (PMID 36419877, 2022). "This is relevant as both TNF-α and GM-CSF suppress tumor cell proliferation, induce tumor regression, enhance anti-tumor co-therapies, and have been investigated in over 50 clinical trials." (PMID 35574362, 2022). "In the case of TNBC, nanobodies against tumor-specific antigens such as TNF-α, EGFR, CD3, CTLA-4, STAT-3, AKT2 among others, have been generated and tested for targeting cancer cells." (PMID 36507540, 2022). "These surface marker alterations, indicative of an activated neutrophil phenotype, were not apparent in neutrophils stimulated with CM of necrotic or TNFα-treated tumour cells." (PMID 35121727, 2022). "We used adipose-derived mast cells (ADMC) sensitized with human anti-HER2/neu IgE which bound to and released MC mediators when incubated with HER2/neu-positive human breast cancer cells (SK-BR-3 and BT-474) resulting in TNF-α mediated, tumor cell apoptosis." (PMID 35433433, 2022). "At first, cells of the TME try to contain the growth of the tumor by the secretion of cytokines such as TNF or INF-γ, trying to recruit immune and inflammatory cellular defense mechanisms." (PMID 36552039, 2022). "The anti-tumor activity of TNF-α has been fully proved, and it is considered to be involved in multiple mechanisms, such as the activation of anti-tumor immune responses and the promotion of cancer cell apoptosis." (PMID 36354990, 2022). "It was recently shown that ADAM17-mediated shedding of the TNF-receptor 1 (TNFR1) is the initiating event of TNFα-induced necroptosis in endothelial cells promoting tumor cell extravasation and metastasis formation." (PMID 35892600, 2022). "For instance, inflammatory cytokines such as IL-1β, IL-6, IL-17, IL-18, IL-23, and TNF-α can lead to tumor growth through activation of pathways such as NF-κB and STAT351–54." (PMID 36085201, 2022). "Tumor development and metastasis are slowed or stopped entirely when interferon and TNF-α are released or membrane bound by NK cells." (PMID 36213442, 2022). "The plasma concentrations of IL-6, IL-10, and TNF-α were significantly increased in the serum of tumour-bearing SID animals compared to the healthy controls." (PMID 36010845, 2022). "TNF-α has been shown to promote the formation and progression of the tumour inflammatory microenvironment." (PMID 35415239, 2022). "The increased expression of TNF-α in CRC tissues and serum are positively associated with tumor recurrence, advancement and metastasis leading to decreased survival of CRC patients." (PMID 35954156, 2022). "Another pro-inflammatory molecule is TNF-α, a multifunctional pro-inflammatory cytokine that regulates different processes, such as inflammation, cell apoptosis, tumor growth, and cell invasion." (PMID 35269666, 2022). "The 4-1BB receptor is expressed mainly in the cells of the immune system and belongs to the tumor necrosis factor (TNF) receptor family but has also been shown to be expressed in tumor cells." (PMID 36547538, 2022). "Continuous bevacizumab treatment promoted the polarization of M2b macrophages in the TME, resulting in TNFα-induced high ESM1 expression in tumor cells in vivo." (PMID 36428773, 2022). "TNF-α is a key cytokine involved in inflammation, immunity, cell homeostasis, and tumor progression." (PMID 36578029, 2022). "During tumor progression, T-cell-mediated antitumor response is significantly impaired, characterized by low secretion of interleukin-2 (IL-2), TNF-α, and interferon-γ (IFN-γ) and a high expression of inhibitory receptors such as PD-1." (PMID 35216168, 2022). "When produced as a recombinant fusion protein, the TNFα-CSG functions as an ECM depletion agent via an immune-mediated mechanism to improve tumor perfusion." (PMID 35273916, 2022).
tumor (continued). "Recent advances in understanding the mechanisms behind ICI treatment have allowed new treatment options such as abatacept and anti-TNFα agents that can reduce drug toxicity and allow continuation of treatment to achieve tumor clearance." (PMID 35455289, 2022). "Increased levels of IFN-γ and TNF-α would promote resistance to anti-tumor treatments by inducing tumor cell stemness and the expression of immune suppressive factors." (PMID 35875098, 2022). "Tumor-infiltrating CD8+ T cells activated by ICIs secrete anti-tumor cytokines such as interferon-γ, tumor necrosis factor-α, interleukin-17, and interleukin-2 (IL-2)." (PMID 36139451, 2022). "Generally, IL-2, IFN-gamma, IFN-alpha, and TNF-alpha signaling can elicit a pro-inflammatory response and demonstrate potent anti-tumor effects in CRC through a direct and indirect mechanism." (PMID 36362062, 2022). "TNF-α is a pro-inflammatory cytokine with diverse roles, e.g., it can favor tumor development, angiogenesis, as well as apoptosis and recruitment of macrophages (resident of the CNS or infiltrates)." (PMID 35057010, 2022). "TRM are also a rich source of type I interferons (IFN), IFN-γ and tumor necrosis factor alpha (TNF-α) which are essential for anti-tumor activity." (PMID 36466880, 2022). "Necroptosis follows signal regulation within tumor cells, and after TNF-α binds to TNFR1 on the plasma membrane, downstream protein molecules are recruited to form complex I." (PMID 36204681, 2022). "CD11b+ myeloid cells and CD11b+F4/80+ macrophages within the tumor also showed a significant increase in TNF-α production due to WGP." (PMID 35140221, 2022). "Upon exposure to hyperthermia, hepatocytes upregulate a host of inflammatory cytokines including TNFα and IL-631,32 that can drive inflammation-mediated carcinogenesis and result in local and remote tumor growth." (PMID 36002545, 2022). "A finding that was confirmed for each of these checkpoints in Ly6C+ tumor-infiltrated monocytes isolated from anti-PD-L1-treated mice, in which we previously demonstrated elevated levels of serological TNF-α." (PMID 35493461, 2022). "In these cases, the anti-TNF-α drugs were suggested to reduce inflammation-induced tumor progression." (PMID 36140220, 2022). "The clear contribution of TNF-α to CRC tumor development and progression can be categorized by studying its secretion time and the type of immune cells secreting it during the process of tumor formation." (PMID 35954156, 2022). "TNF-α-induced tumor initiation and tumor promotion are mediated by MMP-9-induced activation of NF-κB and AP-1-dependent signals in tumor cells." (PMID 35840633, 2022). "In muscle tissues of mice, the inflammatory markers such as IFN-γ, IL-1, and tumor TNF gene are upregulated by spaceflight, accounting for muscle wasting." (PMID 35874841, 2022). "At the same time, the activated CTLs release large amounts of cytokines, such as interferon-γ (IFN-γ) and tumor necrosis factor-α (TNF-α), leading therefore to the formation of the tumor microenvironment and subsequent recruitment of T cells." (PMID 36046045, 2022). "TFs of AP-1, regulating TNFα, IL-6 and SELE are implicated as oncogenes or tumor suppressors in many cancers with drug development programs targeting cJun, JunB, JunD, cFos, FosB, Fra1 and Fra2." (PMID 36371231, 2022). "Research has shown that cytokines such as INF-γ, TNFα, and IL-2 can enhance the anti-tumor function of CAR-T cells." (PMID 35935930, 2022). "The RGD peptide selectively binds the integrins such as ανβ3, overexpressed in tumor blood vessels, while TNF-α, an inflammation-induced cytokine, is applied to trigger tumor vascular damage." (PMID 36544135, 2022). "As an alternative indicator of systemic anti-tumor immunity, we profiled serum levels of two inflammatory cytokines, IFNγ and TNFα." (PMID 35780226, 2022). "Our results showed that most of the differential genera were involved in tumor immunity pathways, such as IL-17 and TNF signaling." (PMID 35145519, 2022).
tumor (continued). "In tumor NK cells, we observed that p38 blockade induced a strong restoration of TNF-α and CD107a production accompanied by increased IFN-γ expression in samples with a reduced production of this cytokine." (PMID 35677052, 2022). "TNFα still causes MCF7 cell apoptosis when it is combined with SM-164 probably because SM-164 degrades a low level of IAP proteins in MCF7 cells, allowing TNFα-activated signaling, such as NF-κB, to result in tumor cell death." (PMID 36119107, 2022). "As tumor suppressors, FoxO proteins increased the expression level of death receptor ligands such as Fas ligand and tumor necrosis factor (TNF) apoptosis ligand, engaged with pro-apoptotic pathways, and blocked cell cycle progression." (PMID 35721149, 2022). "On the other hand, TNF-α can also act as a tumor suppressor via rebuilding the TME by enhancing cytotoxic T cell activity, promoting DCs maturation, and preventing tumor angiogenesis." (PMID 35954156, 2022). "Mononuclear macrophages are mainly responsible for phagocytosis, while releasing lysosomal enzymes, TNF-α and other factors to kill tumor cells and virus-infected cells." (PMID 36440446, 2022). "TNF, although initially discovered to induce cancer cell death, can also possess pro-tumor properties." (PMID 36555441, 2022). "TNF-α is an endogenous tumor promoter that is generated by neoplastic cells or cells in the tumor microenvironment." (PMID 35481240, 2022). "At the KEGG pathway aspects, the RMGS was associated with many tumor-related pathways, such as the ECM receptor interaction, cell adhesion molecules, cytokine–cytokine receptor interaction, and TNF signaling pathway." (PMID 35754835, 2022). "The level of infiltrating CD8+ T lymphocytes in the tumour tissue and secretion of TNF-α and IFN-γ levels increased." (PMID 35729552, 2022). "Monocytes from PBMCs were cultured in a medium with GM-CSF, and IL-4, and matured in TNFα, followed by pulsing with tumor lysate and Keyhole Limpet Hemocyanin (KLH)." (PMID 36011029, 2022). "The relevance of these results is supported by the fact that the pro-inflammatory cytokine TNFα has been shown to act as a tumor promoter in early events in tumors, regulating a cascade of cytokines, chemokines, adhesions, MMPs and pro-angiogenic activities." (PMID 36004343, 2022). "Treatment with combination therapy increased the plasma concentrations of IFN-γ, TNF-α, IL-2, and IL-6, indicating that tumor-infiltrating Treg cells gained CD4 effector function." (PMID 36090972, 2022). "Nonetheless, ADIPOR1 mRNA levels were in negative correlation with gene sets related to pathways important for tumor progression, such as the TNF-α NFκB signaling pathway and MTORC, thus supporting the protective role of ADIPOR1 in CRC." (PMID 36429712, 2022). "M0 macrophages can be stimulated by interferon-γ (IFN-γ) into activated anti-tumor M1 macrophages which exerts cytotoxic effect on tumor by secreting cytokines like IL-2 and TNFα." (PMID 36253762, 2022). "Studies suggest that the double knockout JNK1−/− results in reduction in tumor burden, tumor proliferation, and cytokine production, including TNFα and IL-6." (PMID 35409206, 2022). "The molecules link between NF‐κB‐activated inflammation and tumour promotion has been proposed, such as IL‐1β, IL‐6 and TNF‐α, which are downstream targets of NF‐κB." (PMID 36124714, 2022). "We found significant correlations between periostin levels in tumor and VEGF-A, IFN-γ, IL-1β, and TNFα concentrations in tumor." (PMID 35056404, 2022). "ORL1 is a specific receptor of oxLDL that mediates most functions of oxLDL, such as NF-κB and TNF-α signalling pathway activation, promoting the formation of foam cells in the vasculature and enhancing the proliferation and metastasis of tumour cells." (PMID 36503493, 2022). "PC saponin, a key class of compounds in PC, can inhibit the proliferation of tumor cells by down-regulating the expression levels of IL-6R, TNF-α and NF-KB in the inflammatory microenvironment of mice." (PMID 35814470, 2022).
tumor (continued). "These transcription factors result in the secretion of pro-inflammatory cytokines that also promote tumor growth, such as TNF-a, IL-1β, and IL-6." (PMID 35053599, 2022). "Apart from the fact that TNFα was involved in cell-to-cell communication in the tumor microenvironment, the inflammatory cytokine had the capacity to induce neovasculogenesis in the liver of NOD-SCID mice." (PMID 36290384, 2022). "TNF-α is primarily formed by macrophages in inflammatory tissues, and it is involved in angiogenesis, wound healing, and tumor formation." (PMID 36124089, 2022). "Tumor growth triggers an inflammatory response around the tumor, which induces the secretion of inflammatory cytokines, such as tumor necrosis factor-α (TNF-α), interleukin (IL)-6, and IL-1β17,18." (PMID 35388147, 2022). "Results showed that the modified baicalin exerted tumor suppression effects, with a 6-fold upregulation of IL-6 and TNF-α in the supernatant of RAW264.7 cells compared with the control group." (PMID 36232344, 2022). "IL-10 in the tumor microenvironment inhibits the production of IFNγ and TNFα; it also downregulates MHC class II in monocytes, establishing TIL anergy, and, in doing so, it enhances tumor growth." (PMID 35203636, 2022). "Although an oversimplification, for charting purposes, the cytokines were split into three groups by their generalized tumor-destroying (IFN-γ, IL-2, and IL-5), tumor-promoting (IL-10 and IL-4), or SIRS-associated (IL-1β, IL-6, CXCL-1, and TNF-α) properties." (PMID 35465347, 2022). "TNF-α, IL-6, and IL-10 were all significantly higher in the Chemotherapy group compared with Tumor group." (PMID 36428795, 2022). "Engineering of CAR T cells to secrete Flt3L increased DC precursors in the bone marrow and tumour, increased intratumoural DC secreting IL-12 and TNF, and inhibited tumour growth." (PMID 35205725, 2022). "Although TAMs has pro-tumor effects in most cases, it can also kill tumor cells by releasing tumor necrosis factor-α (TNF-α) and interferon-γ (IFN-γ) to promote the immune response of Th1 (helper cells)." (PMID 35935838, 2022). "Results of preclinical studies suggest that this peptide-cytokine fusion product represents a valuable strategy for delivering TNF to tumor vessels in an amount sufficient to break the biological barriers that restrict drug penetration in cancer lesions." (PMID 35890309, 2022). "In particular, ID2 expression downregulated TNF-α, which induced proliferation of Tregs at the tumor site." (PMID 35806328, 2022). "Tumor cells can change the immune status of the tumor microenvironment by upregulating programmed death-ligand 1 (PD-1), and related inflammatory factors such as TNF-a, IL-6, and IL-1β increase significantly." (PMID 36189281, 2022). "Intriguingly, TNFα expression was higher in tumor biopsy specimens of EAC patients with pre-existing GERD, suggesting an amplified response mediated by the consistent exposure of esophageal tissue to bile reflux during GERD." (PMID 35123116, 2022). "M1 macrophages secrete cytokines such as TNF-α, which have anti-tumor, anti-angiogenesis and activation of adaptive immunity." (PMID 35935970, 2022). "It is well known that CD8+ T lymphocytes killing tumor cells are mediated by exocytosis using cytotoxic granules perforin and granzyme to directly destruct tumor cells, or by releasing cytokines, such as IFN-γ and TNF-α, to poison tumor cells indirectly." (PMID 35530361, 2022). "We found that cisplatin-pretreated tumor cells stimulate neutrophils which expressed higher levels of cytotoxic effectors, including TNF-α, GZMB, and ELANE, and pro-inflammatory cytokines, such as CCL2, CCL3, CXCL10, CXCL11, and IL12." (PMID 35784745, 2022). "A further study by the same group was conducted in 2020, showing the in vitro secretion of RANTES and—when recognition of U87MG EGFRVIII+ tumor cells by CAR-NK cells occurred—a significant secretion of TNF-α, IFN-γ, IL-2, and IL-6 cytokines." (PMID 35203609, 2022).
tumor (continued). "Through qRT-PCR on clinical samples, expression of NRP1, IGF2R, SERPINA3 and TNF were significantly upregulated in tumor tissue, while ICOS and DES were significantly downregulated." (PMID 36406134, 2022). "F. nucleatum modulates host immunity and tumor microenvironment by inducing mucin secretion and inflammatory cytokine TNF-α expression, while P. anaerobius promotes intracellular cholesterol biosynthesis to induce colon cell proliferation." (PMID 35882981, 2022). "The tumor necrosis factor (TNF) can cause bleeding, necrosis, and killing of tumor tissue, which can cause anti-infection inflammatory response and take a role in regulation and induction of immune cells." (PMID 36313628, 2022). "GSEA analysis of our RNA-seq data from the PSaRC318 tumor at relapse demonstrated upregulation of multiple immunoregulatory pathways including TNFα/NFκB, inflammatory response, TGFβ, IL6, IL2, and IFNγ." (PMID 36187937, 2022). "Tumor-induced systemic inflammation promotes tumorigenesis, invasion, and metastasis via inflammatory mediators, such as tumor necrosis factor-alpha, interleukin-6, and interleukin-10." (PMID 35410196, 2022). "CD8+ T cells combines with T-cell receptors and tumor cells to generate IFNg, TNF, and granzyme B and eliminate tumor cells." (PMID 36505472, 2022). "According to the study with a pancreatic-cancer-induced mouse model, TNF-α accelerated tumor growth and metastasis." (PMID 36140220, 2022). "It is clear that IL-17 and TNF-α have an antitumor effect and are essential for suppressing tumor growth." (PMID 36298611, 2022). "Like NF-kB, TNF-α also plays a vital role in the regulation of the inflammatory process encountered during tumor development, but studies have shown that NF-kB signaling causes TNF-α mediated invasion and metastasis of OSCCs." (PMID 35936727, 2022). "Over the last decade, TNFα has been found to be involved in tumor cell proliferation, aggressiveness, EMT, tumor recurrence, and metastasis." (PMID 36290384, 2022). "The IFN-γ level and TNF-α level in the supernatant of tumor homogenates also increased, as shown by ELISA." (PMID 35688951, 2022). "We believe that new formulations focusing on the codelivery of TP and TNF-α nanomaterials for targeting tumor tissues can be a better solution for the antitumor effects of TP." (PMID 36110523, 2022). "Other studies have shown that non-small cell lung cancer cells that metastasize to the brain have high levels of CD15 expression; they interact with TNF-α-activated CD62E on endothelial cells to mediate adhesion of tumor cells to microvessels." (PMID 36338717, 2022). "After M2 polarization, inflammatory factors such as TNF-α and IL-6 are produced, which promote cancer in tumor microenvironment; this effect is more obvious in hypoxic environments." (PMID 35145526, 2022). "The activation of infused CAR T cells and interaction with tumor cells leads to the release of several cytokines including IL-2, soluble IL-2Rα, IFNγ, IL-6, tumor necrosis factor (TNF)-α, soluble IL-6R, and GM-CSF." (PMID 35845425, 2022). "Other experiments performed in mice have shown that the neutralization of TNF-α can convert inflammation-promoted metastatic growth to inflammation-induced tumor regression, dependent on IFN-induced TRAIL expression." (PMID 35406450, 2022). "TNF-α and IL-1β promote tumor cell growth; however, IL-6 receptor expression is down-regulated in these tumors." (PMID 36338717, 2022). "The MVD and budding were assessed using a light microscope Results: We found significantly higher concentrations of periostin, VEGF-A, IFN-γ, IL-1 β, IL-17 and TNFα in the tumor samples compared with surgical tissue margins." (PMID 35056404, 2022). "They stimulate Treg differentiation and secrete several factors (e.g. TGFβ, TNFα, and IL-10) to create a favorable environment for tumor progression and to inhibit the anti-tumor effects of immune cells." (PMID 35805132, 2022).